AGXT (alanine--glyoxylate aminotransferase)
Description:
Peroxisomal aminotransferase that catalyzes the transamination of glyoxylate to glycine and contributes to the glyoxylate detoxification. Also catalyzes the transamination between L-serine and pyruvate and contributes to gluconeogenesis from the L-serine metabolism.
Synonyms: AGT; SPT; AGT1; SPAT; AGXT1; PH1; TLH6; Ser-PyrAT
Tractability: Small molecule: a structure with a bound ligand is known; a high-quality ligand is known. PROTAC: its protein half-life has been measured; a small molecule that binds it is known.
Target class: Enzyme; Transferase
Gene: Protein-coding gene on chromosome 2 (240,868,543 to 240,881,531, forward strand). Ensembl gene ENSG00000172482.
Subcellular location: Peroxisome
Subcellular location (Human Protein Atlas): Vesicles
Pathways (Reactome):
Metabolism: Glyoxylate metabolism and glycine degradation
Protein localization: Peroxisomal protein import
Gene Ontology:
Molecular function: alanine-glyoxylate transaminase activity; amino acid binding; identical protein binding; L-serine-pyruvate transaminase activity; protein binding; protein homodimerization activity; pyridoxal phosphate binding; transaminase activity; alanine-oxo-acid transaminase activity
Biological process: glycine biosynthetic process; glyoxylate catabolic process; glyoxylate metabolic process; L-alanine catabolic process; L-cysteine catabolic process; L-serine catabolic process
Cellular component: peroxisomal matrix; peroxisome; cytosol; cytoplasm
Genetic constraint (gnomAD): Loss-of-function variants: 42 observed, 43.42 expected, observed/expected ratio (o/e) 0.97, 90% interval 0.75 to 1.25. The upper end of that interval is the gene's LOEUF score, 1.25, which puts it in group 5 of 6, group 1 being the genes least tolerant of losing a copy. Missense variants: 525 observed, 495.73 expected, observed/expected ratio (o/e) 1.06, 90% interval 0.99 to 1.14. Synonymous variants: 244 observed, 215.14 expected, observed/expected ratio (o/e) 1.13, 90% interval 1.02 to 1.26.
Gene-disease validity (ClinGen):
ClinGen rates the evidence that AGXT causes each of these diseases.
alanine glyoxylate aminotransferase deficiency (autosomal recessive): Definitive. Any disorder of plasmalogen biosynthesis in which the cause of the disease is a mutation in the AGXT gene.
Homologues: Orthologues: macaque AGXT (93% identical), chimpanzee AGXT (92% identical), dog AGXT (84% identical), pig AGXT (83% identical), rat Agxt (79% identical), guinea pig AGXT (79% identical), mouse Agxt (77% identical), tropical clawed frog agxt (67% identical), zebrafish agxta (58% identical), zebrafish agxtb (57% identical), Drosophila melanogaster Agxt (44% identical), rabbit AGXT (44% identical), and 1 more. Paralogues in human: PSAT1 (15% identical).
Diseases named in the same sentence as AGXT in open-access papers:
AGXT is named in the same sentence as 56 diseases in open-access papers, as found by Europe PMC text mining. Sharing a sentence is not in itself a finding about the gene and the disease. The quoted sentences say what the papers report.
primary hyperoxaluria type 1 (72 papers, 2009 to 2026). A rare disorder of glyoxylate metabolism characterized by the accumulation of oxalate due to a deficiency of the peroxisomal hepatic enzyme L-alanine: glyoxylate aminotransferase (AGT). "AGT deficiency, due to recessive pathogenic changes in the AGXT gene, results in calcium oxalate accumulation and kidney stones, a condition known as primary hyperoxaluria type 1 (PH1)." (PMID 40495747, 2025). "AGXT loss-of-function mutations cause primary hyperoxaluria type 1, an autosomal recessive disorder characterized by calcium oxalate deposition in the kidney and progressive renal failure." (PMID 41150091, 2025). "Primary hyperoxaluria type 1 is a rare autosomal recessive disease resulting from mutations in the alanine-glyoxylate aminotransferase AGXT gene." (PMID 40632478, 2025). "Genetic testing confirmed primary hyperoxaluria type 1 (PH1) with two pathogenic AGXT gene mutations: c.33dupC and Gly170Arg." (PMID 40585464, 2025). "Agxt-1 is orthologous to human AGXT; the AGXT gene mutation can cause primary hyperoxaluria type I in rats." (PMID 38248852, 2024). "In patients with Primary Hyperoxaluria Type 1—a genetic mutation in alanine-glyoxylate aminotransferase—plasma oxalate concentrations range from 3.7 to 14.6 μM." (PMID 36326479, 2023). "Five had a pathogenic variant in the AGXT gene leading to the diagnosis of primary hyperoxaluria type 1." (PMID 37464296, 2023). "Primary hyperoxaluria type 1 (PH1) is an autosomal recessive disorder characterized by the deficiency of the hepatic enzyme alanine-glyoxylate aminotransferase." (PMID 37803380, 2023). "Primary hyperoxaluria type 1 (PH1)—OMIM #259900—is a rare recessive autosomal disorder caused by a deficiency of the liver peroxisomal enzyme alanine-glyoxylate-aminotransferase (AGT), which catalyzes the conversion of glyoxylate to glycine." (PMID 35986861, 2023). "Another example of the added value of assessing the effect of genetic variants with Missense3D-PPI is p.Gly41Arg in the alanine glyoxylate aminotransferase (AGXT) human enzyme (UniProt ID P21549), which causes type I primary hyperoxaluria (MIM 259900)." (PMID 37356905, 2023). "Primary hyperoxaluria type 1 is caused by mutations in the AGXT-gene, which encodes alanine-glyoxylate aminotransferase, a pyridoxal 5′ -phosphate-dependent enzyme." (PMID 36704142, 2022). "Primary hyperoxaluria type 1 is a rare, severe disease caused by a deficiency of the alanine-glyoxylate-aminotransferase (AGT)." (PMID 36704142, 2022). "Primary hyperoxaluria type 1 is a rare recessive autosomal disorder caused by alanine-glyoxylate-aminotransferase (AGT) deficiency and is the most common and severe of three types of primary hyperoxaluria." (PMID 36704142, 2022). "Primary hyperoxaluria type I (PH1) is caused by AGXT gene mutations that decrease the functional activity of alanine:glyoxylate aminotransferase." (PMID 35601556, 2022). "Primary Hyperoxaluria type 1, the most severe form, is caused by a deficiency in alanine-glyoxylate aminotransferase (AGT), a liver-specific peroxisomal enzyme responsible for the transamination of glyoxylate to glycine." (PMID 33678172, 2021). "The AGXT c.508G > A (p.Gly170Arg) variant (4.4%) is previously well defined as one of the most common variants associated with primary hyperoxaluria type 1." (PMID 34082749, 2021). "Primary hyperoxaluria type 1 (PH1) is a genetic autosomal recessively inherited disorder due to mutation in the alanine-glyoxylate aminotransferase (AGXT) gene." (PMID 32569165, 2020). "On the basis of the presented clinicopathological data, an inherited form of type I primary hyperoxaluria characterized by severe chronic crystalline (oxalate) nephropathy was diagnosed in seven Zwartbles sheep homozygous for the AGXT missense variant." (PMID 33003365, 2020).
primary hyperoxaluria type 1 (continued). "Primary hyperoxaluria type 1 is caused by mutations in the AGXT gene encoding the alanine-glyoxylate aminotransferase (AGT), a pyridoxine-dependent liver enzyme that catalyzes the conversion of glyoxylate to glycine." (PMID 26380104, 2015). "These are the first cases of primary hyperoxaluria type 1 to be diagnosed by clinical manifestations and AGXT gene mutations in mainland China." (PMID 24934730, 2014). "Alanine-glyoxylate aminotransferase is a peroxisomal enzyme, of which various missense mutations lead to irreversible kidney damage via primary hyperoxaluria type 1, in part caused by improper peroxisomal targeting." (PMID 22529745, 2012). "Primary hyperoxaluria type 1 (PH 1) is a rare genetic condition due to mutations in the AGXT gene." (PMID 39869204, 2025). "Primary hyperoxaluria type 1 (PH1) is a rare autosomal recessive metabolic disease caused by mutations in the AGXT gene that encodes the liver-specific peroxisomal alanine-glyoxylate aminotransferase (AGT) that catalyses the transamination of glyoxylate to glycine." (PMID 38182795, 2024). "Primary hyperoxaluria type 1 was detected by AGXT variants in one patient." (PMID 34821949, 2022). "Variants in AGXT are known to cause type I primary hyperoxaluria in dogs and humans." (PMID 33003365, 2020). "Primary hyperoxaluria type 1 (PH1) is a rare autosomal recessive disorder resulting from mutations in the alanine-glyoxylate aminotransferase (AGXT) gene, leading to excessive systemic deposition of calcium oxalate." (PMID 41972717, 2026). "Primary hyperoxaluria type 1 (PH1) is a rare genetic disorder caused by hepatic oxalate overproduction due to alanine-glyoxylate aminotransferase (AGXT) deficiency." (PMID 41480893, 2026). "Primary hyperoxaluria type 1 (PH1) is a rare autosomal recessive disorder caused by AGXT mutations, leading to hepatic oxalate overproduction, nephrolithiasis, and progressive renal failure." (PMID 41275431, 2025). "Mutations leading to a deficiency of alanine-glyoxylate aminotransferase (AGT), encoded by the AGXT gene, can lead to primary hyperoxaluria type 1 (PH1)." (PMID 40943222, 2025). "Primary hyperoxaluria type 1 (PH1) is a genetic disorder caused by mutations in AGXT, encoding alanine-glyoxylate aminotransferase (AGT), that lead to accumulation of oxalate from the liver and the formation of kidney stones and associated damage." (PMID 38785523, 2024). "Primary hyperoxaluria type 1 (PH1) is the most frequent and severe form of the disorder, resulting from a deficiency of the hepatic peroxisomal enzyme alanine-glyoxylate aminotransferase (AGXT)." (PMID 37803380, 2023). "Primary hyperoxaluria type 1 (PH1) is caused by pathogenic variants in the AGXT gene leading to a deficiency of the liver-specific peroxisomal enzyme alanine glyoxylate aminotransferase (AGT), which catalyzes the transamination of glyoxylate to glycine." (PMID 36151119, 2022). "Primary hyperoxaluria type 1 (PH1) is a rare autosomal recessive genetic disorder caused by mutations in the AGXT gene." (PMID 36704142, 2022). "Recently, they were successfully used for the long-term expression of a gene encoding an alanine-glyoxylate aminotransferase (AGT) in patients with primary hyperoxaluria type 1 (PH1), a rare kidney disorder that causes recurrent kidney stones." (PMID 31069169, 2019). "Primary hyperoxaluria type 1 (PH1) is the most common and severe of the PHs, due to mutations in the AGXT gene (coding for AGT), with a high incidence of kidney failure as early as infancy." (PMID 39769031, 2024). "Primary hyperoxaluria type 1 (PH1) is due to a shortage in the hepatic peroxisomal enzyme alanine-glyoxylate aminotransferase (AGT)." (PMID 38399458, 2024). "Lumasiran was developed by Alnylam for the treatment of primary hyperoxaluria type 1 (PH1), a rare genetic disorder caused by mutations of the AGXT gene." (PMID 35213992, 2022).
primary hyperoxaluria type 1 (continued). "Primary hyperoxaluria type 1 (PH1) is a rare, autosomal recessive genetic disease resulting from mutations in the AGXT gene." (PMID 34616753, 2021). "By literature reviewing, among the five genes, four have been well documented in HCC, including: ALDOB, IGFBP3, CYP2E1 and TOP2A, while AGXT was mostly studies in primary hyperoxaluria type 1, there are little reports of AGXT in HCC." (PMID 31771612, 2019). "The underlying genetic defect of primary hyperoxaluria type 1 (PH1)—mutation of the AXGT gene encoding enzyme alanine-glyoxylate aminotransferase—leads to systemic accumulation of oxalate deposits in many tissues, except the liver, where the enzyme is localized." (PMID 29322327, 2018). "Primary hyperoxaluria type 1 (PH1), is a rare and heterogeneous disease and one of major causes of renal insufficiency in Tunisia, caused by mutations in the AGXT gene." (PMID 28619084, 2017). "Primary hyperoxaluria type 1 (PH1, OMIM 259900) is a rare autosomal recessive disorder caused by a functional deficiency of the liver-specific peroxisomal enzyme alanine:glyoxylate aminotransferase (AGT, EC 2.6.1.44) due to mutations in the AGXT gene." (PMID 27670739, 2016). "Primary hyperoxaluria type 1 [MIM 259900], a more severe form of the disease caused by mutations in AGXT, is characterized by very severe growth failure." (PMID 26908616, 2016). "Such oxidative damage could impair peroxisomal AGXT localization, as seen in primary hyperoxaluria type I, creating a vicious cycle of glyoxylate mishandling and urate overproduction." (PMID 41150091, 2025). "Non-alcoholic fatty liver disease (NAFLD), leading to non-alcoholic hepatosteatosis (NASH), apparently down-regulates the activity of the hepatic enzyme alanine-glyoxylate aminotransferase (AGXT), the enzyme which, when mutated, is responsible for primary hyperoxaluria type 1." (PMID 36766999, 2023). "Primary hyperoxaluria type I (PH1) is a rare autosomal recessive disease caused by an enzymatic defect of the alanine-glyoxylate amino-transferase, an hepatocyte peroxisomal enzyme coded by the AGXT gene." (PMID 33959570, 2021). "Primary hyperoxaluria type 1 was ruled out as no alanine-glyoxylate aminotransferase (AGXT) mutations were identified and oxalate excretion in urine was within the normal range." (PMID 34217267, 2021). "Primary hyperoxaluria type 1 (PH1) is a rare autosomal recessive metabolic disorder resulting from deficient hepatic alanine‐glyoxylate aminotransferase (AGT) activity, which is caused by mutations in the AGXT gene." (PMID 41275431, 2025). "Primary hyperoxaluria type 1 (PH1) is a rare, autosomal recessive disease characterized by hepatic overproduction of oxalate due to a deficiency in the peroxisomal enzyme alanine–glyoxylate aminotransferase (AGT), which is encoded by the AGXT gene." (PMID 35913563, 2023). "In primary hyperoxaluria type 1 (PH1), which is caused by mutations in alanine-glyoxylate aminotransferase (AGT), siRNA therapy in the mice and non-human primates has shown potential in reducing the expression of glycolate oxidase (GO) by targeting GO mRNA." (PMID 34631795, 2021). "Among the five genes, four (ALDOB; CYP2E1; IGFBP3; TOP2A) were well documented HCC related genes, while AGXT was mostly studies in primary hyperoxaluria type 1, but had not been reported in HCC." (PMID 31771612, 2019). "Here we applied a computational approach to predict and analyze the metabolic alterations occurring in hepatocytes lacking alanine:glyoxylate aminotransferase (AGT), a peroxisomal enzyme encoded by the AGXT gene and mutated in primary hyperoxaluria type 1 (PH1)." (PMID 27239044, 2016).
primary hyperoxaluria (39 papers, 2011 to 2026). A hereditary disorder characterized by excessive oxalate production, leading to hyperoxaluria. "Accumulating evidence has linked AGXT dysfunction and primary hyperoxaluria with liver disease, with clinical studies demonstrating significant liver involvement in PH1 patients being more pronounced." (PMID 41275431, 2025). "But other truncating variants in the AGXT gene are reported as pathogenic in the Clinvar database for primary hyperoxaluria." (PMID 37803380, 2023). "Primary hyperoxaluria (PH) is an autosomal recessive disorder of oxalate metabolism caused by pathogenic variants in either of three genes (AGXT, GRHPR or HOGA1)." (PMID 36151119, 2022). "Primary hyperoxaluria type I (PH1) is a rare metabolic disease caused by mutations in the AGXT gene causing loss-of-function in the alanine:glyoxylate aminotransferase (AGT) enzyme." (PMID 36557898, 2022). "Primary hyperoxaluria occurs due to deficiency of the liver peroxisomal enzyme alanine:glyoxylate-aminotransferase encoded by the AGXT gene." (PMID 33138774, 2020). "Herein, we present evidence that an ovine type I primary hyperoxaluria is due to a missense variant in the AGXT gene." (PMID 33003365, 2020). "PH1 (OMIM # 259900) represents the most common and severe type of primary hyperoxalurias, caused by mutations in the AGXT gene encoding the liver peroxisomal enzyme alanine:glyoxylate aminotransferase (AGT; EC 2.6.1.44)." (PMID 28969594, 2017). "AGXT mutation leads to primary hyperoxaluria type I (PH1), which is a rare disorder with deposition of calcium oxalate crystals primarily in the urinary tract." (PMID 28394947, 2017). "Primary hyperoxaluria type I (PH I) is the most abundant of the three subgroups of primary hyperoxaluria (70–80%), caused by the incorrect sorting of hepatic enzyme alanine-glyoxylate aminotransferase (AGT) to the endosomes instead of the peroxisomes." (PMID 23840917, 2013). "However, primary hyperoxaluria and AGXT dysfunction have recently been associated with liver disease and MASLD12,15,20,21." (PMID 39333384, 2024). "Moreover, the Zwartbles-specific missense variant in the AGXT gene was predicted as deleterious by both prediction tools and was subsequently pursued as a functional candidate, due to the gene’s previous involvement in human primary hyperoxaluria." (PMID 33003365, 2020). "Disorders of oxalate metabolism were noted on 7 genetic results of primary hyperoxaluria genes (Type 1 AGXT, Type 2 GRHPR, and Type 3 HOGA1) in 7 patients (6%)." (PMID 40126616, 2025). "Dent disease (with inclusion of CLCN5 and OCRL1 genes) and primary hyperoxaluria (PH) (with inclusion of AGXT and HOGA1 genes) were identified with high frequency." (PMID 35612621, 2022). "Primary hyperoxalurias (PHs) are rare autosomal recessive diseases of the glyoxylate metabolism; PH1 is caused by mutations in the AGXT gene, PH2 in GRHPR and PH3 in HOGA1." (PMID 35218550, 2022). "In primary hyperoxaluria, approximately 70% of cases are PH type 1 (PH1), in which an alanine-glyoxylate aminotransferase (AGXT) gene mutation occurs in liver peroxisomes." (PMID 34837989, 2021). "Definitive diagnosis of primary hyperoxaluria (PH) currently utilizes sequential Sanger sequencing of the AGXT, GRPHR, and HOGA1 genes but efficacy is unproven." (PMID 25629080, 2015). "Since type 1 accounts for about 80 % of cases of primary hyperoxaluria, the AGXT gene should be screened first." (PMID 26380104, 2015). "Primary hyperoxaluria type I (PH1) is an autosomal recessive inborn error of metabolism caused by mutations in the AGXT gene, coding for the enzyme alanine-glyoxylate aminotransferase (AGT)." (PMID 24205397, 2013). "Moreover, a systematic analysis of liver tissues from patients with primary hyperoxaluria revealed high rates of chronic liver disease, hepatic inflammation and fibrosis in patients with AGXT dysfunction." (PMID 39333384, 2024).
primary hyperoxaluria (continued). "Alanine-glyoxylate aminotransferase (AGT) is one of the aminotransferases that has raised most biomedical interest, since its deficiency causes primary hyperoxaluria type I (PH1), a rare inherited entity with unique features in terms of cellular and molecular biology of human disease." (PMID 23956997, 2013).